MTOR (mechanistic target of rapamycin kinase)
Diseases named in the same sentence as MTOR in open-access papers (continued):
Sharing a sentence is not in itself a finding about the gene and the disease.
tuberous sclerosis (continued). "These mouse models have shown that dysregulation of the mTOR signaling pathways, induced by Tsc1 and Tsc2 inactivation, results in a Tuberous Sclerosis-like phenotype." (PMID 31245336, 2019). "The International tuberous sclerosis complex consensus conference held in 2012 recommended mTOR inhibitors as the first-line treatment for RAML when enlarged to 3 cm or more, even when asymptomatic." (PMID 29587809, 2018). "Suppression of hyperactive mTOR signaling by rapamycin rescues the long-term memory impairment in animal models with tuberous sclerosis or overexposure to cannabinoids." (PMID 29317619, 2018). "For example, individuals with Tuberous Sclerosis, a disorder characterized by uncontrolled upregulation of mTOR, would worsen with further upregulation of mTOR." (PMID 29391397, 2018). "mTOR inhibitors reduce seizures in patients with tuberous sclerosis complex, a phacomatosis where a constitutively activation of mTOR exists." (PMID 29566708, 2018). "Hyperactive mTOR signaling cascade and overactivation of local dendritic translation have recently been reported in mouse models of tuberous sclerosis, Fragile X and Down’s syndrome, all of which display intellectual disability." (PMID 29317619, 2018). "Extrinsic IL-7 survival signal maintains naïve T cell quiescence, a mechanism that relies on tuberous sclerosis (TSC) function to keep mTOR activation in check." (PMID 28443090, 2017). "Downstream, the PI3K/AKT pathway regulates cellular metabolism via the tuberous sclerosis (TSC)/mammalian target of rapamycin (mTOR) pathway." (PMID 29176977, 2017). "Rapamycin is used to treat tuberous sclerosis, a disease caused by mutations in either of the genes TSC1 or TSC2, both of which are involved in the regulation of the mTOR pathway." (PMID 28086757, 2017). "mTOR inhibitors are effective treatment for not only cancer, but for the brain and renal tumors of tuberous sclerosis." (PMID 28086757, 2017). "Hyperactivation of the mTOR pathway, due to loss of function mutations in the TSC1 and TSC2 genes, upstream inhibitors of mTOR, gives rise to Tuberous Sclerosis Complex (TSC)." (PMID 28341829, 2017). "Rather, the evidence for mTOR-signaling as a promising common ASD pathway candidate arise mostly from in vivo research into syndromic autisms such as Tuberous Sclerosis (TS), PTEN-related syndrome, Neurofibromatosis Type 1 (NF-1) and FXS." (PMID 28420080, 2017). "For instance, mutations in PTEN, neurofibromatosis (NF1) or in the tuberous sclerosis complex, cause an overactivation of the PI3K/Akt/mTOR pathway, leading to autism-related behavior, tuberous sclerosis and macrocephaly." (PMID 26877878, 2016). "Everolimus, a mammalian target of rapamycin (mTOR) inhibitor, has demonstrated efficacy in treating subependymal giant cell astrocytomas (SEGAs) and other manifestations of tuberous sclerosis complex (TSC)." (PMID 27351628, 2016). "Additional potential benefits exist, as mTOR inhibitors have been shown to reduce the size of renal AMLs that are present in most adults with tuberous sclerosis and also to improve the characteristic facial rash (facial angiofibromatosis)." (PMID 27515417, 2016). "As AKT phosphorylates mTOR directly, dysregulation of the mTOR pathway can result in abnormal cortical brain development as seen in patients with Tuberous Sclerosis." (PMID 26933590, 2015). "The PI3K-Akt/mTOR pathway is dysregulated in monogenic disorders associated with ASD including Fragile X, tuberous sclerosis, neurofibromatosis, and PTEN." (PMID 26146533, 2015). "In the present study, we demonstrate that, in contrast to fragile X syndrome, tuberous sclerosis, neurofibromatosis 1 and macrocephaly which exhibit increased mTOR pathway components, the mTOR pathway is decreased in idiopathic autism." (PMID 25627160, 2015).
tuberous sclerosis (continued). "Dysregulation of mTOR signaling can cause a variety of diseases, including tuberous sclerosis (mutations in TSC1, TSC2), hemimegalencephaly (AKT3, PIK3CA, MTOR) and focal cortical dysplasia (DEPDC5, AKT3, MTOR)." (PMID 26302787, 2015). "Extensive research concerning tuberous sclerosis complex has led to a breakthrough in the treatment of this disease, enabling pharmacotherapy with mTOR inhibitors." (PMID 26220190, 2015). "Since the finding that the tuberous sclerosis genes TSC1 and TSC2 are suppressors of the mTOR signaling pathway, mTOR inhibitors have been used as a treatment approach in tuberous sclerosis." (PMID 26248290, 2015). "When TSC2 protein is lost, (e.g. in tuberous sclerosis), mTOR remains constitutively activated to drive cell growth." (PMID 24318044, 2014). "For example, tuberous sclerosis is a condition, in which inherited or spontaneous mutations of the TSC1 or TSC2 gene lead to a failure of inhibition of the mTOR (mammalian target of rapamycin) pathway, causing abnormal cell proliferation." (PMID 25400619, 2014). "Topical use of the mTOR inhibitor rapamycin is an effective treatment for the skin tumours (angiofibromas) in tuberous sclerosis complex, which is also characterised by mTOR deregulation." (PMID 24910976, 2014). "The applicability of this approach towards ASD has been shown for the closely connected mTOR pathway in mouse models of tuberous sclerosis." (PMID 24860643, 2014). "Activation of the mTOR pathway has been linked to the cytopathology and epileptogenicity of malformations, specifically Focal Cortical Dysplasia (FCD) and Tuberous Sclerosis (TSC)." (PMID 25005575, 2014). "The hyperactivity of mTOR is a key factor in the pathophysiology of tuberous sclerosis, and its inhibition can be of benefit with regard to tumour development and recurrence." (PMID 23401839, 2013). "Its use as an mTOR inhibitor for the treatment of tuberous sclerosis has recently been translated from transgenic mouse models to man." (PMID 23667480, 2013). "To date, everolimus is the only mTOR inhibitor clinically approved for treatment of tuberous sclerosis." (PMID 24379984, 2013). "TSC1 is mutated in tuberous sclerosis, acts downstream of PTEN in the mTOR pathway and affects cortical lamination, neuronal migration and axon pathfinding." (PMID 22457638, 2012). "An important role of the mTOR pathway in clear cell RCC (CCRCC) is supported by the occurrence of these cancers in patients with tuberous sclerosis, who have a constitutively activated mTOR pathway." (PMID 20701793, 2010). "Such involvement with mTOR signaling is a feature of several hamartoma syndromes, including tuberous sclerosis complex, with which BHDS shares phenotypical characteristics." (PMID 20403193, 2010). "The mTOR signaling pathway is essential for protein translation, cell growth and proliferation in the physiological setting, whereas excessive mTOR activity has been implicated in pathophysiology of renal cyst formation in ADPKD and tuberous sclerosis." (PMID 40486517, 2025). "Notably, hyperactivation of astrocytic mTOR in the tuberous sclerosis complex increases the release of gliotransmitters and thus promotes neuronal hyperexcitability." (PMID 39893345, 2025). "In cases of tuberous sclerosis complex (TSC), mTOR has been found to play a critical role in the epileptogenesis associated with TSC, as inhibitors of mTOR, such as the drug rapamycin, have been effective in reducing the intensity and frequency of seizures for TSC patients." (PMID 40943279, 2025). "Mutations in the TBC1D7 gene do not cause tuberous sclerosis complex, but its deficiency can lead to symptoms linked to mTOR abnormalities, like intellectual disability and megalocephaly." (PMID 39901197, 2025).
tuberous sclerosis (continued). "Meanwhile, human midgestation CGE interneuron progenitors are the putative cell of origin for tuberous sclerosis complex caused by germline TSC1/2 mutations, which inhibit mTOR signaling, and are associated with subependymal nodules and subependymal giant cell astrocytoma." (PMID 39495206, 2025). "Given the central role of this pathway in multiple cellular processes, it is not surprising that mTOR pathway dysregulation is a key mechanism underlying several neurological disorders, including Tuberous Sclerosis Complex (TSC)." (PMID 40792287, 2025). "Additionally, small-molecule modulators such as mTOR inhibitors (e.g., Everolimus) have demonstrated neurocognitive benefits in individuals with tuberous sclerosis complex, illustrating the potential of disease-specific neuroprotective strategies." (PMID 41179085, 2025). "In conditions like tuberous sclerosis and epileptic encephalopathy, dysregulation of the mTOR pathway leads to increased cell proliferation and heightened neuronal excitability, mediated by the upregulation of receptors for excitatory neurotransmitters such as glutamate." (PMID 39867454, 2024). "mTOR downregulation provides significant benefits to patients with tuberous sclerosis." (PMID 38390862, 2024). "Meanwhile, mTOR inhibitors have several other effects; in terms of safety, mTOR inhibitors have proven relatively safe long-term oral agents in human solid organ transplantation and tuberous sclerosis." (PMID 38734930, 2024). "Interestingly, clinical trials targeting mTOR inhibition have been carried out for certain symptoms (subependymal astrocytoma, angiomyolipoma) in tuberous sclerosis (TSC) patients and is also considered an option for treating neurological symptoms." (PMID 38255309, 2024). "The decreased cerebral blood flow resulting from the blockade of the S6K1 branch of mTOR signaling could potentially offer therapeutic benefits in the treatment of tuberous sclerosis-ASD in humans." (PMID 38570425, 2024). "Animal experimental studies have shown that ketogenic diet may reduce seizures in children with tuberous sclerosis by inhibiting mTOR pathway signaling and blocking mTOR pathway activation." (PMID 39539663, 2024). "This is, for example, the case of tuberous sclerosis complex (TSC), in which the dysregulation of the neurotransmission of GABA, resulting from genetic mutations of the mTOR pathway, has been established to underlie the development of both epilepsy and ASD in these individuals." (PMID 36833240, 2023). "Metformin may be a primary candidate for this, since it has recently demonstrated clinical activity in the model brain tumors driven by the metabolic master regulator mTOR in tuberous sclerosis patients." (PMID 34487222, 2022). "MTOR inhibition is an effective treatment for many manifestations of tuberous sclerosis complex." (PMID 35804402, 2022). "Since a decrease in melanocyte numbers and melanosome maturation hasbeen reported in ash-leaf macules of tuberous sclerosis patients harboringloss-of-function variants in TSC1 or TSC2, which encode upstream inhibitors of mTOR, westudied melanogenesis in patients with MTOR-related HI." (PMID 33833411, 2021). "For example, there are a number of trials including rapamycin/everolimus, targeting the mTOR pathway, for the treatment of tuberous sclerosis complex and related WS; retigabine for the treatment of KCNQ2-related WS; and topiramate for the treatment of CACNA1E-related WS." (PMID 34055682, 2021). "Of note, hyperactivation of mTORC1 signaling is associated with several neurological disorders, such as autism, AD, and tuberous sclerosis, and suppression of mTORC1 using compounds that inhibit mTOR signaling has been shown to be an effective treatment in several clinical trials." (PMID 34499406, 2021).
tuberous sclerosis (continued). "The aim of this study was to evaluate the effect of everolimus, a mammalian target of rapamycin (mTOR) inhibitor, on red blood cell parameters in the context of iron homeostasis in patients with tuberous sclerosis complex (TSC) and evaluate its effect on cell size in vitro." (PMID 34202704, 2021). "Similarly, there are advances in the molecular targeting (everolimus, sirolimus) of the mTOR pathway for the treatment of tuberous sclerosis." (PMID 34607926, 2021). "Also, some neurodevelopmental disorders such as focal cortical dysplasias, tuberous sclerosis complex and syndromic autism spectrum disorder (ASD) are thought to arise due to the effects of mTOR mutations during fetal development." (PMID 34512273, 2021). "The inadvertent over-activation of mTOR also has the potential of tumorigenesis (for example resulting from the loss of tumor suppressor TSC1/2 function, as in Tuberous Sclerosis), but also loss of autophagy function, glucose intolerance via IRS-1 feedback inhibition and learning impairment." (PMID 34215308, 2021). "An illustrative example of a genetic defect in the mTOR pathway is tuberous sclerosis." (PMID 32087199, 2020). "Enhanced mTOR signaling in the brain was first identified in resected specimens from patients with tuberous sclerosis complex and focal cortical displasia, both considered as focal cerebral cortical malformations that usually cause drug-resistant seizures in children." (PMID 33202963, 2020). "The mTOR signaling pathway is dysregulated in many neurodevelopmental disorders including autism and Fragile X Syndrome, as well as in cortical malformations such as Focal Cortical Dysplasia and Tuberous Sclerosis." (PMID 32876565, 2020). "This could be explained by increasing the expression of DNA-damage-inducible transcript 4 (DDIT4), which can activate tuberous sclerosis 2, and decreasing the expression of Akt, both of which result in inhibiting the expression of mTOR." (PMID 32455017, 2020). "Advances in our understanding of the regulatory role of tuberous sclerosis gene products (hamartin/tuberin) in the mechanistic target of rapamycin (mTOR) signaling pathway have led to the identification of effective therapy (mTOR inhibitors) for a rare disorder, once considered uniformly fatal." (PMID 29946430, 2018). "The Akt-mTOR pathway is dysregulated in multiple animal models of monogenic causes of ASD, including fragile X mental retardation, Rett Syndrome and tuberous sclerosis, whereas IGF-1 ligands may improve neurodevelopmental symptoms in Rett Syndrome." (PMID 30111726, 2018). "One of the best-studied examples of the role of aberrant mTOR activity in the pathology of neurodevelopmental disease is in tuberous sclerosis, a multisystem genetic disorder that can include intellectual disability, developmental delay, and autism spectrum disorder (ASD)." (PMID 30083288, 2018). "Transgenic mouse models of tuberous sclerosis such as Tsc2+/− and Tsc1+/− exhibit increased activity in the mTOR pathway, which is accompanied by deficits in long-term potentiation and spatial learning, which can be reversed by chronic treatment with a rapamycin, a mTOR pathway inhibitor." (PMID 30083288, 2018). "mTOR pathway is specifically activated in tumors arising in patients with tuberous sclerosis (TSC)." (PMID 27555886, 2016). "Thus we provide important insight into the molecular pathology of tuberous sclerosis and present an experimental system for future investigation of disease-modifying compounds beyond mTOR inhibitors and development of comprehensive therapies for TSC." (PMID 27655340, 2016). "Tuberous sclerosis complexes (TSCs) normally inhibit Rheb-directed mTOR activation, and mutations in TSC proteins (TSC1-hamartin, TSC2-tuberin) constitutively activate Rheb-mTOR-pS6K and increase cell size." (PMID 27795403, 2016).
tuberous sclerosis (continued). "Tuberous sclerosis (TSC) is a monogenic disease resulting from defects of the TSC1 or TSC2 genes, which encode the proteins forming hamartin-tuberin tumor suppressor complex, the mammalian target of rapamycin complex (mTOR)." (PMID 27680012, 2016). "Tuberous sclerosis (TSC) is a neurodevelopmental disorder that is caused by autosomal dominant mutations in the TSC1 or TSC2 tumor suppressor genes, which function as negative regulators of the mTOR signaling cascade." (PMID 26483618, 2015). "Also, we have shown that in the hamartoma syndrome tuberous sclerosis, normoxic elevation of mTOR activity enhances the PTEN tumor suppressor gene expression via upregulation of Hif1α." (PMID 25333702, 2014). "The drug everolimus, an mTOR inhibitor, is approved for the treatment of tuberous sclerosis." (PMID 25593991, 2014). "Enhanced mTOR pathway activation has been reported in LEAT, such as GG and DNT, suggesting a pathogenic link between these tumor entities and focal MCD, such as FCD ILAE Type IIb and cortical tubers in tuberous sclerosis complex (TSC)." (PMID 24858213, 2014). "It inactivates the tuberous sclerosis TSC1/2 inhibitors of mTOR." (PMID 23389114, 2013). "The first human disease definitively linked to aberrant mTOR activation is tuberous sclerosis complex, a rare genetic disease characterized by nonmalignant tumors of the brain, kidneys, heart, lungs, eyes, and skin." (PMID 24379984, 2013). "This review will focus on the role of mTOR inhibitors in the treatment of tuberous sclerosis." (PMID 23730262, 2012). "Indeed, our findings encourage an extension of clinical trials of mTOR inhibitors from patients presenting genetic forms of autism-related disorder, like tuberous sclerosis, to more numerous populations of schizophrenic patients." (PMID 23027611, 2012). "Upon activation, AMPK induces formation of the tuberous sclerosis complex to inhibit phosphorylation of the mammalian target of rapamycin (mTOR), which triggers autophagy through two downstream signaling partners, ribosomal protein S6 kinase and 4E-binding protein 1(4-eBP1)." (PMID 21386904, 2011). "These intriguing results indicate that pharmacological suppression of heightened mTOR signaling in Tuberous Sclerosis patients might be of therapeutic value." (PMID 20126541, 2010). "These disruptions underlie several neurodevelopmental disorders, including tuberous sclerosis complex (TSC), focal cortical dysplasia (FCD), and hemimegaloencephaly (HME), which arise from either germline or somatic mutations in mTOR pathway components." (PMID 41301687, 2025). "In another trial, the use of everolimus, an mTOR inhibitor, on intellectual disability in children with tuberous sclerosis complex (TSC) revealed minimal improvement in cognitive functioning or other neuropsychological deficits in children with TSC." (PMID 40434434, 2025). "Consistent with the idea that mTOR signaling dysfunction could be a common mechanism for autism, monogenic syndromic disorders, which can exhibit ASD such as tuberous sclerosis (TSC), PTEN-associated ASD, and neurofibromatosis-1, have mutations that directly affect mTOR pathway components." (PMID 38525876, 2024). "mTOR hyperactivation is observed in Tuberous Sclerosis Complex (TSC) which presents with epileptic seizures and autism-like traits." (PMID 38390593, 2024). "Patients with well-defined conditions stemming from mTOR overactivation, such as tuberous sclerosis (TSC) and lymphangioleiomyomatosis (LAM), present more suitable study subjects due to their targeted treatment needs and longer life expectancy." (PMID 39148107, 2024). "Rapamycin has been used clinically for several conditions, including the treatment of refractory epilepsy in patients with tuberous sclerosis complex (TSC) whose mTOR pathway is naturally activated." (PMID 36645181, 2023).